CDKN1B (cyclin dependent kinase inhibitor 1B)
Diseases named in the same sentence as CDKN1B in open-access papers (continued):
Sharing a sentence is not in itself a finding about the gene and the disease.
melanoma (51 papers, 2005 to 2025). A malignant, usually aggressive tumor composed of atypical, neoplastic melanocytes. "For example, loss of nuclear CDKN1B expression is correlated with a worse 5-year survival of primary melanoma patients in Kaplan–Meier analysis, but gain of cytoplasmic CDKN1B was associated with a poor 5-year survival of metastatic melanoma patients." (PMID 32467670, 2020). "We also identified new mutations in the CDK and PI3K/AKT/mTOR pathways in clear cell RCC brain metastasis tumors, while a melanoma brain metastasis also showed a single new CDKN1B gene mutation, suggesting the potential for CDK inhibitor therapy in these patients." (PMID 36507516, 2022). "In both melanoma cell lines, the most pronounced changes in CDKN1B mRNA levels were observed in treated cells at 12 h." (PMID 41373567, 2025). "It is known that miR-221 downregulates expression of some genes with tumor-suppressing function in melanoma, e.g., cyclin-dependent kinase inhibitor 1B (CDKN1B/p27Kip1), and c-KIT receptor (CD117)." (PMID 37298110, 2023). "In contrast, cyclin-dependent kinase inhibitor 1bb (cdkn1bb), the ortholog of human CDKN1B, was downregulated at 1 dpa and in melanoma." (PMID 38020918, 2023). "In preclinical models, miR-221 plays a pro-oncogenic role in melanoma cells by downregulating the expression of the cellular cycle modulator p27Kip1/CDKN1B." (PMID 38201222, 2023). "Although anti-oncogenic function of CDKN1B in melanoma has been reported, exosomal miR-199a-1-5p targeting of CDKN1B in the recipient cells has not been reported prior to this study." (PMID 35397647, 2022). "By use of CRISPR-Cas9 genome editing, we introduced sequences encoding EGFP at the endogenous locus of CDKN1B and sequences encoding mCherry at the endogenous locus of MKI67, into Mel-RM and A375 melanoma cells." (PMID 34646389, 2021). "At the transcriptional level, MITF controls genes involved in cell survival (BCL2, HIF1A, BCL2A1), migration (DIAPH1, MET) and proliferation (CDK2, TBX2, CDKN1B), providing important signals for growth of melanoma cells." (PMID 34289891, 2021). "MicroRNA miR‐222 is involved in melanoma development by controlling tumor progression through the down‐modulation of its target genes: p27Kip1/CDKN1B, c‐KIT and c‐FOS." (PMID 30499222, 2019). "In our experiments, the increased nuclear localization of CDKN1A and CDKN1B in both melanoma cell lines after TSPC treatment supports the antitumor activity of this compound." (PMID 28231799, 2017). "Focusing on melanoma, we previously showed that miR-221&222 play a dynamic role regulating proliferation and progression repressing several antineoplastic targets (e.g., p27Kip1/CDKN1B, c-KIT receptor and c-FOS)." (PMID 26912358, 2016). "The observed changes in the expression of the CCND1 and CDKN1B genes may indicate their possible impact on cell cycle arrest and decreased melanoma cells proliferation potential." (PMID 41373567, 2025). "Focal adhesion kinase‐integrin β1 signaling regulates CDKN1A and CDKN1B expression in disseminated cancer cells, and is essential In the present study, human melanoma cells treated with intermediate doses of dacarbazine showed similar alterations of cell distributions in different cell cycle phases." (PMID 36533319, 2023). "However, with the progression of melanoma, the expression of CDKN1B was significantly lower in the melanoma." (PMID 35397647, 2022).
melanoma (continued). "Our previous results showed that miR-221&222 are key factors for melanoma development and dissemination, as they control the progression of the neoplasia through the down-modulation of several direct targets, as p27Kip1/CDKN1B, c-KIT receptor and c-FOS, all playing antineoplastic functions." (PMID 26912358, 2016). "Besides 10 well-studied melanoma genes in the training set, CDKN1B was top ranked melanoma gene in remaining 412 genes from the test set." (PMID 26424083, 2015). "Exosomal crosstalk between melanoma cells with high and low metastatic potential promoting invasiveness was demonstrated as delivery of functional miR-199a-1-5p, which participated in the inactivation of cyclin-dependent kinase inhibitor 1B (CDKN1B), a cell cycle inhibitor." (PMID 36674479, 2023). "CDKN1B was shown to be downregulated and the PI3K/AKT pathway activated in primary melanoma cells after exosomal transfer of miR-222, which was accompanied by increased proliferation and induced invasive and chemotactic capabilities in primary melanoma cells." (PMID 36674479, 2023). "In contrast, in cells treated with the Tbx2-specific siRNA Tbx2 expression was extinguished in almost all cells examined whereas Cdkn1b expression was strongly upregulated in the cytoplasm (in MCF-7 cells) and in the nucleus (in B16 melanoma cells)." (PMID 23341776, 2013). "The miRNAs miR-221 and miR-222 down-regulate p27Kip1/CDKN1B and the c-KIT receptor mRNA levels, which leads to progression of neoplasia through enhanced proliferation and reduced differentiation of melanoma cells." (PMID 21949788, 2011). "For example, miR-221/222 were found to down-regulate p27Kip1/CDKN1B and the c-KIT receptor, which controls the progression of neoplasia leading to enhanced proliferation and reduced differentiation in melanoma cells." (PMID 21072171, 2010). "Since the role of miR-199a-1-5p/CDKN1B axis in melanoma has not been reported, the clinical relevance of CDKN1B was evaluated in human melanoma using the clinical TCGA database, ACLBI database, GEPIA2 database and OncoLnc database." (PMID 35397647, 2022). "Furthermore, miR-221 can facilitate cell cycle progression and proliferation via down-regulation of the tumor-suppressor p27Kip1/CDKN1B and the receptor tyrosine kinase c-KIT, thereby promoting melanoma progression both in vitro and in vivo." (PMID 31906510, 2020). "PSMD14 knockdown significantly induced the expression of p21 mRNA in melanoma cells, but not the expression of p27 mRNA, whose gene name is CDKN1B." (PMID 33154524, 2020). "Similarly, analysis of the melanoma TCGA dataset revealed that GREB1 gene expression was positively correlated with the expression of proliferative marker genes (CDK2, MYC, CCND1, and LIG1) and negatively correlated with CDKN1B." (PMID 37658191, 2023).
hepatocellular carcinoma (43 papers, 2009 to 2025). A malignant tumor that arises from hepatocytes. "Clinically, low expression of CDKN1B has been associated with advanced stage of hepatocellular carcinoma while elevated CDKN1B expression serves as a favorable prognostic marker for better HCC survival rate." (PMID 33598459, 2021). "Here we report that PATZ1 regulates cell proliferation by directly regulating CDKN1B (p27) in hepatocellular carcinoma cells." (PMID 33598459, 2021). "In human hepatocellular carcinoma cells, miR-221-3p was found to control cyclin-dependent kinase inhibitor 1B (p27Kip1) and cyclin-dependent kinase inhibitor 1C (p57Kip2) expression." (PMID 25052466, 2014). "Hepatic fibrosis and hepatocellular carcinoma are closely related to CDKN1B." (PMID 38476236, 2024). "Moreover, the downregulation of miR-221 by α-pinene was shown to participate in the suppression of hepatocellular carcinoma progression via inducing cell cycle arrest and apoptosis through activating cellular factors, including CDKN1B." (PMID 33066509, 2020). "The upregulation of miR-221/222 can promote the growth of hepatocellular carcinoma (HCC) cells by increasing the number of S-phase cells, and the oncogenic activity of miR-221 is believed to be realized through the regulation of CDKN1B." (PMID 38476236, 2024). "In summary, CDK1, CCND1, RAF1, CDKN1B and BTRC were defined as top 5 hub target-genes, and the patients with hepatocellular cancer with high expression of CDK1 showed poor prognosis." (PMID 35836300, 2022). "In hepatocellular carcinoma, miR-221 has been well known to promote cell survival and growth via the regulation of various tumor suppressors, such as PTEN and CDKN1B." (PMID 33066509, 2020). "Like HSV-1-infected hepatoma cells, the upregulation of CDKN1B in CD8+ effector T cells following LCMV infection might not result in hearing impairments if it occurs during the specification of the otic vesicle, but possibly could decrease the proliferation of hair cells and supporting cells." (PMID 33419104, 2021). "Unlike CMV that degrades CDKN1B in fibroblast cells, Sánchez-Quiles and coworkers reported that HSV-1 infection elevates the expression of CDKN1B in human hepatoma cells." (PMID 33419104, 2021).
gastric cancer (38 papers, 2008 to 2025). A primary or metastatic malignant neoplasm involving the stomach. "In contrast, CDKN1B gene amplification is associated with poor prognosis for gastric carcinomas." (PMID 37039257, 2023). "Others have been reported to have good potential to be prognostic biomarkers for CRC (CDKN1A, CDKN1B), stomach cancer (MMP2,) and esophageal cancer (EGFR, PIK3CA,)." (PMID 35681633, 2022). "The LncRNA UCA1, which is upregulated in gastric cancers, recruits EZH2 (enhancer of zeste homolog 2) to the promoters of the genes that encode p27 (CDKN1B) and the sprouty RTK signaling antagonist 1 (SPRY1) to mediate the repressive H3K27me3-trimethylation." (PMID 36010595, 2022). "Gene amplifications of CCND1 and CDKN1B are potential candidates to serve as prognostic markers for the stratification of patients based on the estimate of survival in the management of gastric cancer patients." (PMID 27781065, 2016). "The tumor-suppressor gene cyclin-dependent kinase inhibitor 1B (P27) is downregulated in gastric cancer cells mainly through proteolytic degradation mediated by the SKP-Cullin1-F-Box (SCF) complex." (PMID 26313918, 2015). "Previous studies have demonstrated that a BAP31 intrabody induced cell death in gastric cancer by inhibiting cyclin-dependent kinase inhibitor 1B (CDKN1B, p27kip1) proteasome degradation." (PMID 38474195, 2024). "This suppresses the expression of CDKN1B and SPRY1 along with their tumor-suppressive activities, thus promoting gastric cancer cell proliferation." (PMID 36010595, 2022). "CDKN1B, which also induces G1 arrest, is repressed by SOX2 in pancreatic cancer cells and gastric cancer cells." (PMID 26846300, 2016). "Interestingly, miR-196a-5p is highly expressed in gastric cancer cells and targets the cell cycle inhibitor CDKN1B (p27kip1), leading to increased cell proliferation, while miR-153-3p acts on AKT3 in lung cancer reducing cell proliferation rate." (PMID 33806113, 2021). "Interestingly, two prototypical Myc-repressed genes, CDKN1B (p27KIP1) and CDKN2B (p15INK4B) 39, 46, 53, 54, showed no response to manipulation of c-Myc in the context of gastric cancer, strengthening the concept that c-Myc regulates gene expression selectively and specifically." (PMID 32292506, 2020).
colon carcinoma (33 papers, 2009 to 2025). "Colon cancer has been reported in one family with a CDKN1B mutation, but manifestation of endocrine disease was unreported, and in silico evaluation or functional studies of the mutation were not described." (PMID 30990521, 2019). "Peroxisome proliferator activated receptor alpha (PPARα), a nuclear receptor that regulates lipid homeostasis, inhibits DNA methyltransferase 1 (DNMT1)-mediated cyclin dependent kinase inhibitor 1A (CDKN1A) and PRMT6-mediated cyclin dependent kinase inhibitor 1b (CDKN1B) to promote colon cancer." (PMID 35004688, 2021).
pancreatic cancer (33 papers, 2002 to 2024). "Conspicuously, we notice that 5 genes (CDK6, E2F3, CCND1, SMAD4 and CDKN1B) are associated with cell cycle, colorectal cancer, pancreatic cancer, chronic myeloid leukemia, and small cell lung cancer in the cluster of Group A." (PMID 26221171, 2015). "In this study we identified a 4-bp deletion in a highly conserved regulatory upstream ORF (uORF) in the 5′UTR of the CDKN1B gene in a patient with a pituitary adenoma and a well-differentiated pancreatic neoplasm." (PMID 23555276, 2013). "Taken together, the results show that miR-221-3p may act as an underlying tumour marker for prognosis prediction in pancreatic cancer and may work by acting on KIT, CDKN1B, RUNX2, and BCL2L11 expression." (PMID 32943991, 2020). "MiR-221 also exhibits a progressive function in various tumors and interferes with tumor suppressor genes, such as PTEN, CDKN1B and BLCL2L11 in pancreatic cancer cell lines." (PMID 33809988, 2021). "This screening also identified CDKN1A (p21) and CDKN1B (p27) as upregulated genes by GPC1-depletion in HPDE cell lines and pancreatic cancer cell lines." (PMID 29245923, 2017). "In the context of epithelial differentiation, the authors have identified the cell cycle inhibitor p27KIP1 (CDKN1B) as a target of KLF4, through which proliferation of pancreatic cancer cells was blocked." (PMID 24429391, 2014). "The result of the PPI network projected four genes (KIT, CDKN1B, RUNX2, and BCL2L11) as hub genes in pancreatic cancer, which may be possible targets of miR-221-3p." (PMID 32943991, 2020). "Interestingly, the same proximal region of CDKN1B promoter was recently shown to contain three cis elements for KLF4 transcription factor close to the AP-2 sites and to be induded by KLF4 in pancreatic cancer cell lines." (PMID 19672266, 2009). "Thus, miR-221-3p may affect the incidence and development of pancreatic cancer by affecting KIT, CDKN1B, RUNX2, and BCL2L11 expression." (PMID 32943991, 2020). "In addition, we examined the hub genes KIT, CDKN1B, RUNX2, and BCL2L11, which may act in pancreatic cancer, and confirmed that the expression of KIT, CDKN1B, RUNX2, and BCL2L11 is indeed affected by miR-221-3p." (PMID 32943991, 2020).
lung carcinoma (32 papers, 2003 to 2025). "In lung cancer cells, KDM5A binds directly to the promoter regions of cyclin D1 and cyclin-dependent kinase inhibitor p27 (KIP1) and promotes G1-S progression by activating cyclins D1 and E1 and suppressing p27 (CDKN1B)." (PMID 33578894, 2021). "Upon NUPR1 depletion, proteins such as CDKN2A, CDKN1A, and CDKN1B, which directly regulate cell cycle progression, are involved in the NUPR1-mediated autolysosomal process, which is consistent with our previous observation in lung cancer cells." (PMID 33542201, 2021). "Besides, NT157 decreased expression of oncogenes BCL2, CCND1, MYB, and MYC and increased genes related to cellular stress and apoptosis, JUN, BBC3, CDKN1A, CDKN1B, FOS, and EGR1 (p < 0.05), favoring a tumor-suppressive cell signaling network in the context of lung cancer." (PMID 36224313, 2022).
glioma (30 papers, 2007 to 2025). A benign or malignant brain and spinal cord tumor that arises from glial cells (astrocytes, oligodendrocytes, ependymal cells). "CELF1 promotes glioma cell proliferation by decreasing the expression levels of CDKN1B within the glioma microenvironment." (PMID 38443798, 2024). "The predominant majority of rat glioma 101.8 tumor cells expressed Cadm2, Cdkn1b, and Ero1a." (PMID 41009560, 2025). "SOX5 can suppress PDGFB (platelet-derived growth factor B)-induced glioma development in mice by inhibiting cell proliferation and inducing acute cellular senescence through the regulation of p27Kip1 (cyclin-dependent kinase inhibitor 1B) and AKT1 (AKT serine-threonine protein kinase)." (PMID 37047365, 2023). "As controls, we utilized normal tissue from the GTEx dataset, and we further evaluated the difference in CDKN1B expression between the controls and cancer tissues from the brain lower grade glioma (LGG), ovarian serous cystadenocarcinoma (OV), thymoma (THYM), and uterine carcinosarcoma (UCS)." (PMID 37432583, 2023). "As expected, curcumol significantly increased the levels of EphB3, p21, and CDKN1B in glioma cells." (PMID 34739394, 2021). "We found that curcumol treatment decreased the binding ability of EZH2 to the promoter of downstream effectors (EphB3, p21, and CDKN1B) and the H3K27me3 modification in the promoter regions of effectors and increased the expression levels of effectors in glioma." (PMID 34739394, 2021). "However, the expression level of both Cdkn1b and Cdkn1a was quite high in rat glioma 101.8." (PMID 41009560, 2025). "In glioma cells, CELF1 is bound to suppress the expression of endogenous CDKN1B and attenuates translation initiation via interaction with the overexpression region of CDKN1B." (PMID 38443798, 2024). "In glioma cells, the tumor suppressor CDKN1B (Cyclin Dependent Kinase Inhibitor 1B) has been identified as a CELF1 target." (PMID 34681716, 2021). "In gliomas, CELF1 is upregulated and promotes cell proliferation by inhibiting CDKN1B." (PMID 40781108, 2025).
ovarian carcinoma (30 papers, 2008 to 2025). A malignant neoplasm originating from the surface ovarian epithelium. "In a global online biomarker validation platform developed to mine all available microarray data in 1287 ovarian cancer patients, CDKN1B expression was found to be associated with survival." (PMID 28122348, 2017). "Polymorphisms in CDKN1B may be associated with reduced susceptibility to cancer, particularly ovarian cancer." (PMID 28122348, 2017). "In summary, our meta-analysis demonstrated some evidence that the rs2066827 polymorphism of the CDKN1B gene may protect against the development of human cancer, especially ovarian cancer and in Caucasians." (PMID 26579796, 2015). "For instance, loss of CDKN1B protein was significantly associated with a relatively shorter time to cell cycle progression and decreased overall survival rates in patients with advanced ovarian cancer." (PMID 23236518, 2012). "BRCA1, CDKN1B, PPP1CC, SKP2, and URI1 were clustered in subnetwork 8 and categorized as shared proteins in PCOS and ovarian cancer, hence suggesting an association between the two." (PMID 31216618, 2019). "We also detected amplification and overexpression of CDKN1B in both A-H and S-H cells; thus, it will be necessary to examine the pathological processes of CDKN1B CNV in advanced-stage ovarian cancer." (PMID 28122348, 2017). "In an earlier study, variants in CDKN1B and CDKNA2/2B were found to be associated with ovarian cancer risk in a combined analysis of 3601 cases and 5705 controls." (PMID 19738611, 2009). "Moreover, CDKN1B/p27 has been suggested to be a potential therapeutic target and prognostic marker in ovarian cancer." (PMID 37635248, 2023). "For example, low CDKN1B expression is indicative of poor prognosis for ovarian cancer." (PMID 33748162, 2021). "In human epithelial ovarian cancer (EOC), exosomal miR-221−3p derived from M2 macrophages promotes cancer growth by reducing the cyclin-dependent kinase inhibitor 1B (CDKN1B)." (PMID 41357196, 2025). "In both ovarian cancer cell lines, SKOV3 and OVCAR3, BRD4 expression decreased, whereas CDKN1A (p21) gene expression and degradation of the cell cycle inhibitor CDKN1B/p27KIP1 (p27) increased in a dose-dependent manner." (PMID 38473320, 2024). "In subnetwork 8, long-term potentiation was identified as a significant pathway, where PPP1CC and PPP1CA directly interacted with three PCOS-ovarian cancer-shared PCOSrps—i.e., BRCA1, PPP1CC, and URI1—and indirectly interacted with two shared PCOSrps (CDKN1B and SKP2)." (PMID 31216618, 2019).